CD44 (CD44 molecule (IN blood group))
Diseases named in the same sentence as CD44 in open-access papers (continued):
Sharing a sentence is not in itself a finding about the gene and the disease.
gastric cancer (continued). "Moreover, CD44 haplotypes have beenshown to significantly associate with the increased incidenceof gastric cancer in Chinese patients." (PMID 31376327, 2020). "Moreover, an association between increased CD44 or CD44v6 tumor expression and worse overall survival OS in gastric cancer (GC) patients has previously been reported." (PMID 32252293, 2020). "Variants of CD44 are also expressed in gastric cancers and promote tumor initiation." (PMID 32849491, 2020). "One of the genes associated with gastric cancer is CD44 gene and its polymorphisms." (PMID 31376327, 2020). "De novo expressed CD44 isoforms containing exon-v6 are frequently associated with gastric cancer (GC) aggressiveness, and may predict chemotherapy response in vitro." (PMID 32842638, 2020). "Also in gastric cancer, activation of the Wnt pathway causes an increase in CD44 as well as Oct-3/4 expression and correlates with an increased proliferation." (PMID 32849491, 2020). "Moreover, we observed that the significant association of variant genotype AG or GG of CD44 rs187116 had a higher risk of CD44 protein expression in gastric cancer compared with those with the WT genotype (AA)." (PMID 29445738, 2017). "This study could therefore evaluate the association between CD44 protein expression and CD44 polymorphism and compare the risk of CD44 protein expression in precancerous gastric lesions and gastric cancer." (PMID 29445738, 2017). "Based on the implications of these previous studies, we hypothesized that CD44 expression may be related to the development of gastric cancer and genetic polymorphisms in CD44 may affect their expression; it may be associated with risk of developing cancer." (PMID 29445738, 2017). "Here we investigated CD44 protein expression and its polymorphisms in patients with chronic gastritis, precancerous gastric lesions, and gastric cancer; and we evaluated our result with the risk of CD44 protein expression and clinicopathological characteristics." (PMID 29445738, 2017). "Alteration frequency of CD44 mutation in colon and gastric cancer was analyzed by using BioPortal." (PMID 27323782, 2016). "In this study, based on the results of bioinformatic analyses, we speculated there may be two reasons for a few studies on CD44 polymorphism in colon and gastric cancer." (PMID 27323782, 2016). "Furthermore, we found that CD44 mRNA is associated with poor overall survival (OS) in colon cancer, while with begin OS in gastric cancer." (PMID 27323782, 2016). "CD44 rs187116 could predict disease recurrence in gastric cancer patients, and the single nucleotide polymorphism (SNP) was associated with CD44 isoform switching." (PMID 27323782, 2016). "Individual expression of CD44 was associated with poor survival in patients with gastric carcinoma." (PMID 25212506, 2014). "Notably, our data showed that amplification of ERBB4 and CD44 was significantly associated with poor prognosis in gastric cancer, is new to the literature." (PMID 22606006, 2012). "In the present study, we identified three frequently amplified genes from 30 candidate genes using real-time quantitative PCR method, including ERBB4, C-MET and CD44, and further explored their association with clinicopathological characteristics and poor survival in a cohort of gastric cancers." (PMID 22606006, 2012). "Cyclin D1 expression at high levels has been associated significantly with poor prognosis of gastric cancer, as observed in gastric cancer samples in which CD44 expression was also higher, indicating a coexpression of these proteins could be a potential biomarker for the severity of the disease." (PMID 36769170, 2023). "In this study, we characterized the expression of MET (including METex14SM), PD-L1, and CD44 in human gastric cancer (GC) cells as well as the differential susceptibility of these cells to tepotinib." (PMID 35884507, 2022).
gastric cancer (continued). "Therefore, rs8193 C allele, associated with higherrisk of gastric cancer, might destabilize CD44 and miR-570interaction." (PMID 31376327, 2020). "Thus, CLDN4 might play a role in integrin signaling, or in CD44 associated with stemness in undifferentiated/CDX2-negative gastric cancer." (PMID 31040910, 2019). "Several recent studies have demonstrated that many polymorphisms in CD44 were correlated with the risk of many cancers, including BC, gastric cancer (GC) and CRC." (PMID 27738347, 2016). "targeted CD44+ gastric cancer cells with hyaluronic acid-modified polyamidoamine dendrimer G5-entrapped gold NCs bound to the METase gene, resulting in repressed tumor growth of gastric cells." (PMID 40548119, 2025). "In gastric cancer patients, CTCs expressing CD44 and EpCAM, sorted by flow cytometry, are highly enriched compared with healthy individuals." (PMID 41440277, 2025). "A cohort study and flow cytometry analysis of 127 gastric cancer patients showed that CD24+CD44+CD54+ EpCAM+ cells were positively correlated with tumour metastasis and were present in untreated patients." (PMID 40665579, 2025). "Through scSDNE analysis, we also elucidated L-R interactions between fibroblasts and immune cells—particularly macrophages—in gastric cancer, where interactions of CD44 with collagen family genes and FN1 emerged as key mechanisms for information exchange." (PMID 40333631, 2025). "A cohort study of 127 untreated gastric cancer patients demonstrated that CD24+CD44+CD54+EpCAM+ cells are bona fide gastric CSCs." (PMID 40665579, 2025). "Remarkably, Liu and colleagues observed Hsp90 overexpression in gastric cancer cell lines that elevated stemness (CD44, Nanog, Sox2, and Oct4) and EMT markers, a defining characteristic that was absent in the Hsp90 knockdown cells." (PMID 39936995, 2025). "To further investigate the roles of CD44 isoforms in gastric cancer development, we performed additional IHC analysis." (PMID 40069421, 2025). "ESRP1 binds to lncRNA CCAT2, which regulates CD44 splicing, promoting the transition from standard CD44 to CD44v6 and facilitating gastric cancer progression." (PMID 40046628, 2025). "Among CD44 isoforms, CD44v6 exhibited the highest expression in gastric cancer tissues, significantly surpassing other isoforms, including CD44s, CD44v3-v5, and CD44v7-v9." (PMID 40069421, 2025). "The findings of the present study suggest that LA considerably suppresses key features of gastric cancer stemness through the Akt/Nrf2/CD44/SOX2 signaling pathways." (PMID 40864800, 2025). "In clinical gastric cancer cases, high levels of SNORA37, CMTR1, ELAVL1, or CD44 were associated with shorter survival and poor outcomes of patients." (PMID 39815331, 2025). "Previous studies demonstrated that ablation of CD44 suppressed gastric tumor development in a transgenic mouse model of gastric cancer." (PMID 40518514, 2025). "EVs derived from stomach cancer cells encapsulate proteins such asclaudin-7, CD44v6, CD44, c-MET, EGFR, EpCAM, and GPC1, all of whichare closely associated with the progression of gastric cancer." (PMID 40720603, 2025). "In our study, we observed that elevated CD44 expression in gastric cancer tissues is related to significant enrichment of the JAK-STAT and cell adhesion pathways, both of which are known to play roles in cisplatin resistance." (PMID 40069421, 2025). "In gastric cancer, miR-665 and miR-760 targeted CD44 and ASGR2; in liver cancer, miR-638 showed broad predictions (e.g., HO-1, PPARα/γ)." (PMID 41378310, 2025). "Both CD44 and PRMT2 were up-regulated in gastric cancer tissues, and associated with unfavorable survival of patients." (PMID 39815331, 2025). "Studies have shown that cells from primary tumors and gastric cancer cell lines isolated via the CD44 marker exhibit characteristics of CSCs." (PMID 40866457, 2025).
gastric cancer (continued). "Given the significant role of CD44 expression in gastric cancer progression, it is crucial to further explore its relationship with other oncogenic properties, such as tumor stemness, to understand its broader impact on tumor biology." (PMID 40069421, 2025). "Brusatol treatment (40 nM) substantially reduced the size of the CD44+ gastric cancer stem cell population." (PMID 40864800, 2025). "Another study identified CD44 in exosomes as a cargo protein that transfers the lymph node metastasis phenotype from cells with high lymphatic metastatic potential to primary gastric cancer cells." (PMID 41440277, 2025). "In gastric cancer, downregulation of CAF‐derived secreted protein acidic and rich in cysteine can lead to dedifferentiation of gastric cancer cells into CD44+/CD24− CSCs via AKT/mTOR signaling pathway." (PMID 41346572, 2025). "In HT1080 fibrosarcoma cells, RHAMM regulates cell proliferation through a β-catenin/c-myc signaling axis, and CD44 can influence gastric cancer cell growth by interacting with FGFR2 and c-myc." (PMID 40178908, 2025). "In gastric cancer with peritoneal metastasis, CD44 was identified as an amplified cancer driver gene." (PMID 41009730, 2025). "Our findings demonstrate that increased NINJ2 expression in chemoresistant gastric cancer cells leads to upregulation of CD44, which in turn promotes vimentin expression and enhances invasive and mesenchymal characteristics." (PMID 40518514, 2025). "To further explore CD44 expression and the specific roles of its isoforms in gastric cancer, we examined clinical gastric cancer samples." (PMID 40069421, 2025). "Previous experimental investigations have led to the development of drugs that target CIC-related pathways in gastric cancer, such as CD44 inhibitors, C-MET (HGFR) inhibitors, and Notch and mTOR inhibitors." (PMID 40518514, 2025). "CD44 regulates cell adhesion, motility, and survival, promoting gastric cancer progression through tumor growth, invasion, and metastasis." (PMID 41378310, 2025). "Based on bioinformatics data analysis, CD44 overexpression was correlated with poor prognosis and metastatic disease in gastric cancer." (PMID 40069421, 2025). "The population of CD44+ cancer stem cells in the control (CTL) human gastric cancer MKN45 cells is 34.3%." (PMID 40864800, 2025). "first reported the relationship between CD44 and GCSCs in six gastric cancer cell lines, and research on GCSCs gradually emerged." (PMID 40110193, 2025). "Next, the proportion of CD44-expressing gastric cancer cells in ECF-R gastric cancer cells (13.4 ± 2.7%) was higher than that in the parental cells (1.4 ± 0.7%)." (PMID 40518514, 2025). "CD44 is one of the most frequently used markers for identifying and isolating gastric cancer stem cells (GCSCs)." (PMID 40866457, 2025). "Previously, we described an extended phenotype of gastric cancer stem cells (GCSCs; CD24+CD44+CD54+EpCAM+) that is associated with metastasis and tumor stage in GC patients." (PMID 39148939, 2024). "Previously, we described the presence of gastric cancer stem cells with the immunophenotype CD24+CD44+CD326+ICAM1+ in the gastric tissue of gastric cancer patients and some cell lines, including AGS." (PMID 39201551, 2024). "TBL1XR1 overexpression increased spheroid formation and upregulated Sox2 and CD44 expression in gastric cancer cells." (PMID 38347836, 2024). "HA can specifically bind to various receptors that are highly expressed in tumor cells, such as cell surface receptor CD44, in a variety of cancers, including breast, lung, and gastric cancers." (PMID 39070787, 2024). "Our research group identified gastric cancer stem cells (GCSCs) with the CD24+CD44+CD326+ICAM1+ immunophenotype isolated from gastric cancer patients." (PMID 39201551, 2024). "In our group, we identified a gastric cancer stem cell (GCSC) subpopulation with the CD24+CD44+CD326+ICAM1+ immunophenotype in patients with gastric cancer." (PMID 39201551, 2024).
gastric cancer (continued). "Overexpression of ACAT1 in gastric cancer cells resulted in decreased expression levels of CD44 and OCT4, while the expression level of CD24 increased." (PMID 39247186, 2024). "In gastric cancer, PGE2 maintains the expression of stem cell-associated proteins (OCT4, CD44, and SALL4) and promotes inflammatory microenvironment formation." (PMID 38704736, 2024). "In gastric cancer cells, short hairpin RNA (shRNA) knockdown of CD44 reduced spheroid formation in vitro, as well as tumorigenicity in vivo." (PMID 38612911, 2024). "CD44 cleavage, shedding and elevated levels of soluble CD44 in the serum of patients is a marker of tumor burden and metastasis in several cancers, including colon and gastric cancers." (PMID 38543304, 2024). "In a similar manner, the formation of the circFNDC3B-IGF2BP3-CD44 mRNA ternary complex serves to stabilize mRNA and upregulates CD44, thereby facilitating the migration and invasion of gastric cancer cells." (PMID 38724502, 2024). "To explore the impact of CDC25A on tumor stemness within gastric cancer, we selected CD44 as a well-established marker for cancer stemness investigation." (PMID 38613794, 2024). "Specifically, gastric cancer cells with enhanced BATF2 expression exhibited significantly lower levels of the cancer stem cell markers CD44, NANOG, and SOX2 than the control cells." (PMID 39629124, 2024). "Previously, our research group reported a GCSC immunophenotype (CD24+CD44+CD326+ICAM1+) in gastric cancer patients." (PMID 39201551, 2024). "DAPT also reduced CD44+ cells in gastric cancer and subsequent Wnt/β-catenin signaling, effectively inhibiting tumorsphere formation." (PMID 38612911, 2024). "This study provides SRGN and CD44 as potential therapeutic targets to reduce IL-8 production in gastric cancer." (PMID 38862740, 2024). "SFN was found to inhibit the activation of SHH pathway, tumorsphere formation capacity, and also decreased the expression of CSC markers such as CD133, CD44, Oct-4 and Nanog in gastric cancer cells." (PMID 36776295, 2023). "Gastric cancer stem cells express high levels of the surface marker CD44 and the stemness-related transcription factor OCT4." (PMID 36838713, 2023). "IL-6 activated the STAT3 signaling pathway and induced cancer stemness by upregulating the expression of OCT4 and CD44 in gastric cancer cells." (PMID 36838713, 2023). "In mouse model, both oral vitamin D intake and injections of 1,25(OH)2D3 overcame gastric cancer growing and CD44 expression, suggesting a potential therapeutic role for vitamin D in gastric cancer management and prevention." (PMID 38274206, 2023). "Studies have shown that IL18 is highly expressed in the serum of gastric cancer patients, and endogenous IL18 can promote the metastasis of gastric cancer by enhancing the expression of CD44 and VGEF and inhibiting the expression of CD70." (PMID 36707882, 2023). "Additional studies are needed to further explore the impact of CD44 isoforms on the development of gastric cancer." (PMID 37667739, 2023). "Amorim and co-workers presented an LbL system using HA and PLL to study the substrates’ interactions with CD44 in two human gastric cancer cell lines that overexpress this receptor (AGS and MKN45)." (PMID 37754116, 2023). "CD44 is not only a marker of gastric cancer CSC, it is functionally participating in the tumorigenicity of gastric cancer cells." (PMID 36918410, 2023). "The knockdown of CD44 reduced the cell surface expression of xCT and suppressed tumor growth in a mouse gastric cancer model." (PMID 37185762, 2023). "Although some previous studies showed increased CD44 levels in spheroid culture with gastric cancer cells, CD44 positivity and expression were lower in spheroid cells in the study." (PMID 37529165, 2023).
gastric cancer (continued). "Increasing evidence suggests that CD44 is extensively overexpressed in other cancer types including gallbladder, prostate, ovarian, oral squamous cell carcinoma, and gastric cancer, correlating with aggressive biological behavior and a poor prognosis." (PMID 37316699, 2023). "A number of studies have found that CD44 is progressively elevated in the Correa's cascade model and plays an active role in the development of gastric cancer." (PMID 36918410, 2023). "Ultimately, under our conditions, we conclude that CD24+CD44+CD54+EpCAM+ cells are true gastric cancer stem cells (GCSCs)." (PMID 36737794, 2023). "Marked infiltration of SPP1-expressing TAMs correlated with a worse clinical course in gastric cancer, the SPP1/CD44 axis potentially associated with stemness properties, and intratumoral heterogeneity linked to resistance to anticancer therapies." (PMID 37190178, 2023). "Generally, the stemness of gastric cancer can be identified by analyzing the expression of cell surface markers (CD44) or stemness-related transcriptional factors (OCT4)." (PMID 36838713, 2023). "(2015) described the presence of glycan STn on CD44 glycoprotein which leads to altered CD44 molecular features such as molecular weight and antibody recognition in gastric cancer." (PMID 37854601, 2023). "The results confirmed that GRP78-overexpressing gastric cancer cells induced macrophage IL-6 expression and that the conditioned medium containing macrophages enriched the CD44+ gastric CSC population through the TGF-β1 signaling pathway." (PMID 36838713, 2023). "Zhu and colleagues showed that GCSCs overexpressed CSC markers including Oct-4, Sox2, Klf4, and CD44 compared to the human gastric cancer cell line SGC7901." (PMID 36776295, 2023). "High CD44 expression was observed in gastric cancer, and its expression correlates with immune cell infiltration." (PMID 37667739, 2023). "Gastric cancer cells lose the expression of the standard CD44 subtype (CD44s) and obtain expression of VARIANT 6 of CD44 (CD44v6) in stiff 3D culture, accompanied by upregulation of EMT, metabolism, and angiogenesis‐related genes." (PMID 35712024, 2022). "The results showed that the overall survival (OS), progression-free survival (PFS) and post-progression survival (PPS) of gastric cancer patients with high CD44 expression were poor, and all P values were less than 0.05." (PMID 36316684, 2022). "In gastric cancer, CD44 was shown to modulate Wnt/β-catenin signaling, which is primarily involved in tumor metastasis and progression." (PMID 36231019, 2022). "The peptide PEP-1 (a short amphipathic peptide that blocks the interaction CD44/HA) reduced the CD44 expression levels in mice models of gastric cancer." (PMID 35785191, 2022). "Experiments have indicated that gastric cancer patients with high CD44 expression have a high recurrence rate and high metastasis rate, and their prognosis is very poor." (PMID 36316684, 2022). "Increased CD44+ in gastric cancer induced cisplatin resistance due to the activation of the Hedgehog pathway." (PMID 35547772, 2022). "By using the UALCAN database, the expression of CD44 in gastric cancer patients with different clinical parameters was analysed." (PMID 36316684, 2022). "As a potential therapeutic prognostic marker of gastric cancer, CD44 has important research value and broad prospects." (PMID 36316684, 2022). "Studies have proven that the positive expression rate of CD44 gradually increases with the progression of slow non atrophic gastritis, chronic atrophic gastritis, intestinal metaplasia, dysplasia, gastric cancer and other processes." (PMID 36316684, 2022). "Compared with cells of a gastric cancer cell line, the expression of CD44 mRNA is significantly higher in gastric cancer stem cells (CSC-Gs)." (PMID 36316684, 2022). "The objective was to explore the prognostic value of CD44 in gastric cancer and the possible mechanism of immune invasion." (PMID 36316684, 2022).